NLRP3 (NLR family pyrin domain containing 3)
Diseases named in the same sentence as NLRP3 in open-access papers (continued):
Sharing a sentence is not in itself a finding about the gene and the disease.
atherosclerosis (continued). "Finally, because macrophage autophagy promotes the clearance of the NLRP3 inflammasome to limit the production of pro-inflammatory interleukin (IL)-1β in atherosclerosis, we next sought to quantify plaque IL-1β levels in our study groups." (PMID 38433753, 2024). "Similarly, exposure to polybrominated diphenyl ethers promotes atherosclerosis through lipid accumulation, NLRP3 inflammasome activation, and pyroptosis." (PMID 38543188, 2024). "While NLRP3 is vital for initiating inflammation and facilitating the immune response, excessive and prolonged activation of the NLRP3 inflammasome can have detrimental effects and contribute to the development of various diseases, including diabetes, atherosclerosis, and gout." (PMID 39333773, 2024). "Thus, atherosclerosis is an inflammatory driven process and the NLRP3 as an early triggering factor and the core of vicious circle." (PMID 36910525, 2023). "In addition, melatonin has been reported to prevent atherosclerosis progression by attenuating NLRP3 inflammasome activation by activating autophagy through the Sirt3/FOXO3a/Parkin signaling pathway." (PMID 37570258, 2023). "To investigate the anti-inflammatory effect of IRN and examine whether IRN inhibit NF-кB /NLRP3 activity in atherosclerosis, we detected the expression of inflammation related factors in LPS-induced HUVECs." (PMID 36906555, 2023). "The NLRP3 inflammasome is important in the immune defense system against fungal, viral, and bacterial infections and has been implicated in immune disorders such as autoimmune diseases, IBD, diabetes, myocardial infarction, and atherosclerosis." (PMID 37104238, 2023). "In addition, multiple cellular dysfunctions can lead to overactivation of the NLRP3 inflammasome to aggravate atherosclerosis." (PMID 37370025, 2023). "While mice with EC-restricted KO of pyroptosis machinery have not been generated to study atherosclerosis, mechanistic insights can still be gained using mouse models with global deficiency of caspase-1 or NLRP-3." (PMID 37894840, 2023). "While NLRP3 inflammasome activation is a promising therapeutic target for the treatment of atherosclerosis, and most of its beneficial effects are seen in experimental studies, developing other NLRP3-modifying agents is necessary to address the limitations of current agents." (PMID 37175869, 2023). "Indeed, in an animal model of atherosclerosis, the inhibition of the NLRP3 inflammasome by MCC950 led to a significant decrease in atherosclerotic lesions." (PMID 37242177, 2023). "Therefore, study of the regulatory mechanism of ALDH2 on NLRP3 will provide new ideas for the treatment of atherosclerosis." (PMID 36910525, 2023). "The reason is that as a human monoclonal antibody targeting IL-1β, canakinumab might exert cardiovascular benefits by mediating the activation of IL-1β and the NLRP3 inflammasome within the kidney, thus contributing to cardioprotection during atherosclerosis." (PMID 37123477, 2023). "Moreover, NLRP3 inflammatory corpuscles are closely related to the occurrence of cardiovascular diseases such as atherosclerosis, myocardial infarction, myocardial ischemia-reperfusion and myocardial remodeling after myocardial infarction." (PMID 37214088, 2023). "The NLRP3 inflammasome activates caspase-1, acts on the precursor molecules of IL-1β and IL-18, and promotes the maturation and secretion of IL-1β and IL-18 to trigger an inflammatory response and further aggravate atherosclerosis." (PMID 37679676, 2023). "For example, vigorous activation of NLRP3 has been demonstrated in atherosclerosis, thus deterring NLRP3 is a feasible intervention without interfering with other inflammasome sensors AIM2, NLRP1, NLRC4, and Pyrin that are responsible for detecting bacteria and virus infection." (PMID 36932407, 2023).
atherosclerosis (continued). "UCP1 depletion leads to hyperactivation of the IL-1β and NLRP3 inflammasome by increasing mitochondrial membrane potential and mitochondrial superoxide, thereby exacerbating endothelial dysfunction, vascular inflammation, and atherosclerosis in obese mice." (PMID 37370025, 2023). "To investigate the anti-inflammatory effect of IRN and examine whether it inhibits NF-кB /NLRP3 activity in atherosclerosis, we tested the expression of inflammation related factors in RAW264.7 induced by LPS." (PMID 36906555, 2023). "Taken together, accumulated evidences have suggested that the P2RX7/NLRP3 signaling pathway may play a crucial role in the pathogenesis of both atherosclerosis and PD." (PMID 37649719, 2023). "These discrepancies might be explained by differences in the mouse models used but also might point to an NLRP3-independent progression of atherosclerosis, eventually driven by the inflammasome-independent cytokine IL-1α." (PMID 37239938, 2023). "We hypothesized that the activation of Nlrp3 inflammasome plays a role in atherosclerosis, and the contrast media serves as its activator." (PMID 36837885, 2023). "In addition, excess ROS production and mitochondrial dysfunction during atherosclerosis have been shown to activate NLRP3 inflammasome formation and boosts mitophagy." (PMID 38020895, 2023). "From these findings, it could be inferred that the NLRP3 inflammasome pathway is crucial in the development of atherosclerosis and that HB is beneficial in reducing the inflammatory response of the host." (PMID 37836470, 2023). "Moreover, the NLRP3 (NLR family pyrin domain containing 3) inflammasome contributes to the progression of atherosclerosis, and inhibiting its assembly in both familial and sporadic PD models reduces dopaminergic neurodegeneration." (PMID 37649719, 2023). "Several new anti-inflammatory and anti-cytokine agents, including but not limited to direct upstream inhibitors of the NLRP3 inflammasome, and natural inhibitors of IL-6, can be expected to be used in atherosclerosis by targeting the NLRP3, IL-1, IL-6 to CRP pathway." (PMID 36873405, 2023). "Furthermore, NLRP3 has recently arisen as a central regulator of atherosclerosis initiation and progression." (PMID 37175608, 2023). "Moreover, miR‐302c‐3p, a targeted negative regulator of NLRP3, blocks EC pyroptosis in a mouse model of atherosclerosis." (PMID 37125240, 2023). "Melatonin may effectively protect smoking-induced vascular damage and reduce atherosclerosis through the Nrf2/ROS/NLRP3 signaling pathway." (PMID 36873396, 2023). "However, dysregulated or excessive NLRP3 inflammasome activation is described in a number of pathologic conditions, including AD, diabetes, gout, autoimmune diseases, and atherosclerosis." (PMID 38139851, 2023). "It has been reported that metformin suppressed NLRP3 inflammasome activation and ameliorated diabetes-accelerated atherosclerosis in apoE−/− mice; meanwhile, it blocked the activation of the NLRP3 inflammasome in macrophages induced by HG through the activation of the AMPK pathway in vitro." (PMID 38067543, 2023). "NLRP3 plays a role in the pathophysiology of numerous diseases, including Parkinson’s disease, diabetes, inflammatory bowel disease, COVID-19 infection, and atherosclerosis, among others." (PMID 36768920, 2023). "While the evidence on a contribution of NLRP3 to glucose metabolism, AT inflammation and atherosclerosis is clear, in the context of NAFLD, which in 20% of the cases progresses to a condition of chronic liver inflammation (non-alcoholic steatohepatitis, NASH), the data are less consistent." (PMID 37239938, 2023). "In atherosclerosis, there may also be a feedforward loop whereby mtDNA-driven NLRP3 activation of caspase-1 inhibits PARKIN-meditated mitophagy, which leads to the accumulation of additional mitochondrial damage and ox-mtDNA release." (PMID 37001140, 2023).
atherosclerosis (continued). "Additionally, NLRP3 inflammasome activation is related to multiple metabolic disorders and chronic inflammatory diseases, including hypertension, diabetes, atherosclerosis and so on, these diseases are closely related to the dysregulation of the endothelium." (PMID 37175227, 2023). "Among those inflammasomes, NLRP3 inflammasome has been well characterized and its activation strongly links to sterile inflammation in a variety of chronic degenerative diseases including atherosclerosis." (PMID 37284455, 2023). "During atherosclerosis, cholesterol crystals evoke NETs to provide the first priming signal for macrophages, whereas the production of pro-IL-1β provides the second signal for the activation of the NLRP3 inflammasome and the release of mature cytokines." (PMID 36851139, 2023). "Moreover, we identified NLRP3, NF-kappaB, NLRP3 macrophages and oxidative stress as research topics in inflammasomes in atherosclerosis research." (PMID 37123477, 2023). "Oridonin has a protective effect on atherosclerosis in ApoE−/− mice, which may be related to the inhibition of NLRP3 and the stabilization of Nrf2." (PMID 37155118, 2023). "Neither of the biologics previously listed has received approval for use in clinical practice as an NLRP3 inhibitor alone, despite the NLRP3-IL-1b inflammasome pathway being a potentially valuable therapeutic target for patients with atherosclerosis and other inflammatory conditions." (PMID 37175869, 2023). "Consequently, NLRP3, which is involved in the pathogenesis of type 2 diabetes mellitus, atherosclerosis, cardiovascular, and neurodegenerative diseases, can be repressed by treatment with NIP3." (PMID 37854633, 2023). "Additionally, other stimuli relevant to atherosclerosis, such as disturbed blood flow, can enhance the activation of the NLRP3 inflammasome." (PMID 37958528, 2023). "Such strategies for harnessing gene-immune signatures may be the future of personalized medicine, whereby a formidable impact of the NETs–NLRP3 inflammasome nexus on atherosclerosis and its affiliated worst outcomes can be curtailed." (PMID 36851139, 2023). "Notably, a strong and positive correlation between NLRP3 and the severity of coronary artery stenosis is further observed in patients with atherosclerosis." (PMID 37336361, 2023). "UCHL5 modified by METTL14/YTHDF1 axis could facilitate the inflammation and vascular remodeling in atherosclerosis by activating the NLRP3 inflammasome." (PMID 37441706, 2023). "Another study have shown that when the function of CMA is damaged during the progression of atherosclerosis, it can increase the activation of inflammatory body NLRP3 and the secretion of IL-1β, so as to promote the progress of vascular inflammation and atherosclerosis." (PMID 37063954, 2023). "While the role of inflammation in atherosclerosis is currently extensively explored, the precise deleterious effects on endothelial integrity and the involvement of molecules, such as NLRP3 inflammasomes, in the pathogenesis and evolution of atherosclerosis remain elusive." (PMID 37175869, 2023). "Several studies have shown that the expression levels of NLRP3 inflammasome components may play a role in the progression of atherosclerosis." (PMID 38004268, 2023). "Several recent studies have indicated that there may be interactions between PCSK9 and the NLRP3 inflammasome, which may contribute to the inflammatory response that drives atherosclerosis development and progression." (PMID 36911736, 2023). "The classical NLRP3 inflammasome pathway is activated by two triggers, whose joint action drives apoptosis-associated speck-like protein (ASC) phosphorylation and produces ASC plaques to create atherosclerosis." (PMID 37836470, 2023). "The accumulating evidence has indicated that the NLRP3 inflammasome plays a key role in the pathogenesis of chronic inflammatory diseases and metabolic disorders, including obesity, hypertension, diabetes, atherosclerosis, depression, stroke, and cancer." (PMID 37763063, 2023).
atherosclerosis (continued). "IL-1β and IL-18, both by-products of NLRP3 inflammasome activation, appear to have a relevant contribution in the occurrence and propagation of atherosclerosis which is corroborated by abundant data obtained from the evaluation of atherosclerotic plaques in rodents and humans." (PMID 37175869, 2023). "Therefore, elevated TyG levels can exacerbate atherosclerosis through an upregulated NLRP3 signaling pathway represented by hsCRP." (PMID 37375712, 2023). "Combining NLRP3 inhibitors with other agents that target other aspects of atherosclerosis., such as lipid metabolism or immune cell recruitment, may provide synergistic effects and enhance therapeutic efficacy." (PMID 37175869, 2023). "In addition, oxidized LDL activates transcription of NLRP3 and pro-IL-1β, promoting atherosclerosis." (PMID 38068879, 2023). "Considering the interconnection of gut microbiota, host inflammation, and atherosclerosis, we formulated a hypothesis that highland barley could attenuate atherosclerosis by modulating the NLRP3 inflammasome pathway through the regulation of gut microbiota." (PMID 37836470, 2023). "In addition to alleviating the pathological process of atherosclerosis, MT has also been found to have cardioprotective effects via inhibiting NLRP3 inflammasome activation and its induced cardiomyocyte pyroptosis in mice with MI." (PMID 37125240, 2023). "This might explain why the role of the NLRP3 inflammasome in the pathogenesis of atherosclerosis is mainly studied in monocytes and macrophages." (PMID 37830572, 2023). "This discovery paved the path for further research into this theory, and abundant examples of NLRP3 activating stimuli related to atherosclerosis are shown; CCs are reported among the most effective activators of the NLRP3 inflammasome that occur during all phases of ATS." (PMID 37175869, 2023). "The present study demonstrated that APN had a protective effect on the development of NAFLD and atherosclerosis and that the mechanism may involve the inhibition of the NLRP3/NF-κB signaling pathway." (PMID 37198205, 2023). "Pyroptosis of ECs driven by inflammasome NLRP3 is the key pathological process of atherosclerosis." (PMID 37743632, 2023). "It is essential to explore the connection among NLRP3 inflammasome, pyroptosis and atherosclerosis, which may shed light on the potential therapeutic strategies that target pyroptosis in atherosclerotic treatment." (PMID 36304814, 2022). "We suspected that miR-99a-5p might inhibit NLRP3 inflammasome activation and promote macrophage autophagy via constraining mTOR, therefore, alleviating atherosclerosis." (PMID 35968506, 2022). "However, the results of NLRP3 inflammasome on atherosclerosis are inconsistent and its molecular mechanism is still uncertain." (PMID 36304814, 2022). "Several studies have also suggested that smoking, hypertension, high sugar intakes, and fatty diets rich in saturated fats may all be responsible for enhanced activation of NLRP3 in myeloid cells of the patients with atherosclerosis." (PMID 36082127, 2022). "The NLRP3 inflammasome has also been found to play a role in atherosclerosis." (PMID 35877579, 2022). "The dysfunction and death of endothelial cells are known for their role in the initiation of atherosclerosis and recently, the NLRP3-mediated pathway has been identified as the main mechanism of pyroptosis in endothelial cells for atherosclerosis at early stages." (PMID 35563294, 2022). "The phagocytosis of oxLDL induces the expression of pro-IL-1β and ROS by the cathepsin B pathway, resulting in activation of the NLRP3 inflammasome, inducing macrophages to secrete IL-1β, and promoting macrophage transfer into foam cells during atherosclerosis." (PMID 36082127, 2022). "Hence, LPS in combination with oxLDL was shown to induce NLRP3 inflammasome activation and IL-1β production by macrophages that contribute to atherosclerosis development." (PMID 36275758, 2022).
atherosclerosis (continued). "Activation of the NLRP3 inflammasome also occurs in atherosclerosis." (PMID 36138973, 2022). "The NLRP3 inflammasome is an important driver of atherosclerosis." (PMID 36006939, 2022). "Taken together, NLRP3 inflammasome plays a key role in the development of atherosclerosis." (PMID 36304814, 2022). "In addition, aberrant activation of the NLRP3 inflammasome is related to several types of inflammatory diseases, including obesity, diabetes, atherosclerosis, nonalcoholic steatohepatitis, gout, and Alzheimer’s disease." (PMID 36589841, 2022). "C1q can induce cytokines and enhance NLRP3 inflammasome to promote atherosclerosis development by initiating a classical pathway while retarding the formation of the necrotic core in plaques via promoting cholesterol efflux from macrophage foam cells and downregulating their apoptosis." (PMID 36248871, 2022). "There is evidence that the production of NLRP3-IL-1β may contribute to the development of accelerated atherosclerosis in clonal hematopoiesis." (PMID 35562903, 2022). "Taken together, NLRP3 inflammasome is largely responsible for the development of atherosclerosis." (PMID 36671400, 2022). "Additionally, the study showed that NLRP3-mediated inflammatory pathways play a critical role in atherosclerosis progression, placing the possibility of specific NLRP3 inhibitors as promising therapies to combat atherosclerosis." (PMID 36082127, 2022). "NLRP3 plays an important role in the formation of atherosclerosis." (PMID 35321239, 2022). "At the same time, WD was suggested to impact epigenetic reprogramming of granulocyte and monocyte precursor cells in NLRP3 inflammasome dependent manner, skewing bone marrow cell differentiation toward myeloid lineages and enhancing so-called “trained immunity” in atherosclerosis." (PMID 36275758, 2022). "Given that overactivation of the NLRP3 inflammasome leads to inflammatory diseases such as Alzheimer’s disease, gout, and atherosclerosis, KA or other agonists of GPR35 might have potential as new therapeutics for NLRP3-triggered diseases." (PMID 36311752, 2022). "Furthermore, NLRP3 inflammasome, Caspase-1, and IL-1β trigger inflammation in the blood vessel wall, thereby leading to atherosclerosis." (PMID 36187801, 2022). "In the presence of excessive dietary cholesterol and an extended feeding period, the NLRP3 inflammasome may play a weaker role in the development of atherosclerosis." (PMID 36082127, 2022). "NLRP3 is an important inflammatory factor involved in atherosclerosis." (PMID 35431939, 2022). "While NLRP3 is essential for the immune response to numerous pathogens, it has primarily gained notoriety due to its role in autoinflammatory and inflammation-based diseases, including type II diabetes, Alzheimer’s disease (AD), atherosclerosis, and gout." (PMID 36127465, 2022). "Several studies have been sprung up in exploring NLRP3 inflammasome in relation to atherosclerosis." (PMID 36304814, 2022). "Notedly, NLRP3 inflammasome components have been upregulated in human atherosclerosis." (PMID 36304814, 2022). "The NLRP3 inflammasome is expected to be a therapeutic target for atherosclerosis." (PMID 36671400, 2022). "Another animal experiment showed that FGF21 reduced ROS production and alleviated atherosclerosis possibly by reducing NLRP3 inflammasome-mediated pyroptosis of vascular endothelial cell, maintaining normal mitochondrial dynamics, and inhibiting VEC endoplasmic reticulum stress." (PMID 35909513, 2022). "It is yet to be determined whether these interactions between gut microbiota and NLRP3 inflammasome activation also directly regulate lipid metabolism, inflammation, oxidative stress, and endothelial dysfunction in the setting of atherosclerosis." (PMID 36082127, 2022). "The NLRP3 inflammasome plays an important role in the pathogenesis of atherosclerosis and may therefore be a promising target for therapeutic approaches." (PMID 36589841, 2022).